ARHGDIA (Rho GDP dissociation inhibitor alpha)
Description:
Controls Rho proteins homeostasis. Regulates the GDP/GTP exchange reaction of the Rho proteins by inhibiting the dissociation of GDP from them, and the subsequent binding of GTP to them. Retains Rho proteins such as CDC42, RAC1 and RHOA in an inactive cytosolic pool, regulating their stability and protecting them from degradation. Actively involved in the recycling and distribution of activated Rho GTPases in the cell, mediates extraction from membranes of both inactive and activated molecules due its exceptionally high affinity for prenylated forms. Through the modulation of Rho proteins, may play a role in cell motility regulation. In glioma cells, inhibits cell migration and invasion by mediating the signals of SEMA5A and PLXNB3 that lead to inactivation of RAC1.
Synonyms: GDIA1; RHOGDI; HEL-S-47e; NPHS8; RHOGDI-1
Tractability: Small molecule: a structure with a bound ligand is known; a high-quality ligand is known; it has a high-quality binding pocket. PROTAC: UniProt records ubiquitination sites on it; ubiquitination databases record sites on it; its protein half-life has been measured; a small molecule that binds it is known.
Gene: Protein-coding gene on chromosome 17 (81,867,719 to 81,871,378, reverse strand). Ensembl gene ENSG00000141522.
Subcellular location: Cytoplasm
Subcellular location (Human Protein Atlas): Cytosol
Pathways (Reactome):
Signal Transduction: Axonal growth inhibition (RHOA activation); Axonal growth stimulation; CDC42 GTPase cycle; RAC1 GTPase cycle; RAC2 GTPase cycle; RHOA GTPase cycle; RHOC GTPase cycle; RHOG GTPase cycle; RHOH GTPase cycle
Gene Ontology:
Molecular function: protein binding; Rho GDP-dissociation inhibitor activity
Biological process: regulation of Rho protein signal transduction; negative regulation of apoptotic process; Rho protein signal transduction; semaphorin-plexin signaling pathway; regulation of synaptic vesicle cycle
Cellular component: cytoplasm; cytosol; extracellular exosome; cytoskeleton; membrane; immunological synapse; nucleus; Schaffer collateral - CA1 synapse
Genetic constraint (gnomAD): Loss-of-function variants: 9 observed, 25.91 expected, observed/expected ratio (o/e) 0.35, 90% interval 0.21 to 0.61. The synonymous counts are far from expectation, so gnomAD's model fits this gene poorly and the ratio says little. Missense variants: 239 observed, 271.14 expected, observed/expected ratio (o/e) 0.88, 90% interval 0.79 to 0.98. Synonymous variants: 166 observed, 114.99 expected, observed/expected ratio (o/e) 1.44, 90% interval 1.27 to 1.64.
Gene-disease validity (ClinGen):
ClinGen rates the evidence that ARHGDIA causes each of these diseases.
nephrotic syndrome, type 8 (autosomal recessive): Moderate. Any nephrotic syndrome in which the cause of the disease is a mutation in the ARHGDIA gene.
Homologues: Orthologues: pig ARHGDIA (98% identical), mouse Arhgdia (97% identical), guinea pig ARHGDIA (97% identical), dog ARHGDIA (85% identical), zebrafish arhgdia (82% identical), chimpanzee ARHGDIA (74% identical), macaque ARHGDIA (74% identical), tropical clawed frog arhgdia (72% identical), rat Arhgdia (71% identical), Drosophila melanogaster RhoGDI (51% identical), Caenorhabditis elegans rhi-1 (39% identical). Paralogues in human: ARHGDIB (68% identical), ARHGDIG (58% identical).